THAP8 (THAP domain containing 8)
Synonyms: FLJ32891
Tractability: PROTAC: ubiquitination databases record sites on it.
Gene: Protein-coding gene on chromosome 19 (36,034,984 to 36,054,739, reverse strand). Ensembl gene ENSG00000161277.
Subcellular location (Human Protein Atlas): Nucleoplasm
Gene Ontology:
Molecular function: protein binding
Cellular component: nucleoplasm
Genetic constraint (gnomAD): Loss-of-function variants: 24 observed, 20.82 expected, observed/expected ratio (o/e) 1.15, 90% interval 0.83 to 1.62. The upper end of that interval is the gene's LOEUF score, 1.62, which puts it in group 6 of 6, group 1 being the genes least tolerant of losing a copy. Missense variants: 399 observed, 337.76 expected, observed/expected ratio (o/e) 1.18, 90% interval 1.09 to 1.28. Synonymous variants: 169 observed, 143.87 expected, observed/expected ratio (o/e) 1.17, 90% interval 1.04 to 1.34.
Homologues: Orthologues: chimpanzee THAP8 (97% identical), macaque THAP8 (92% identical), pig THAP8 (69% identical), dog THAP8 (66% identical), Drosophila melanogaster CG13894 (8% identical). Paralogues in human: THAP7 (18% identical), THAP1 (18% identical), THAP3 (18% identical), THAP2 (16% identical), THAP6 (9% identical), ARL14EP (8% identical), ARL14EPL (3% identical).
Diseases named in the same sentence as THAP8 in open-access papers:
THAP8 is named in the same sentence as 1 disease in open-access papers, as found by Europe PMC text mining. Sharing a sentence is not in itself a finding about the gene and the disease. The quoted sentences say what the papers report.
infection (1 paper, 2023). The state of being infected such as from the introduction of a foreign agent such as serum, vaccine, antigenic substance or organism. "For comparison, the highest positive fold-change for RVA G5P infection was only 17-fold for THAP8 (involved in cell apoptosis regulation)." (PMID 37515094, 2023).